BCL2 (BCL2 apoptosis regulator)
Diseases named in the same sentence as BCL2 in open-access papers (continued):
Sharing a sentence is not in itself a finding about the gene and the disease.
cancer (continued). "In order to evaluate the mRNA expression levels of apoptotic-associated genes including p-53, caspase-3, caspase-9, Bax, and Bcl-2 in MCF-7 and WEHI-164 cancer cells, qRT-PCR was carried out." (PMID 33122979, 2020). "Challenging HCT116 cells with ABT-737 (targeting BCL-2, BCL-XL and BCL-W), WEHI-539 (targeting BCL-XL) and ABT-199 (targeting BCL-2) only marginally killed cancer cells 15–18." (PMID 32312973, 2020). "Designed to inhibit both BCL-xL and BCL-2, ABT-263 has a higher pro-apoptotic efficacy in cancers overexpressing BCL-xL." (PMID 33023187, 2020). "Among these, BH3 mimetics are small molecules developed to inhibit pro-survival proteins (BCL-2, BCL-xL, MCL-1), unleashing BAX/BAK to promote MOMP and apoptosis onset in otherwise aberrantly surviving cancer cells." (PMID 32722518, 2020). "Existing studies have reported the regulatory mechanism of Bcl-2 and CCND1 in cancer cells, including the post-transcriptional downregulation by miR-15 and miR-16." (PMID 33490079, 2020). "Using the Genomics of Drug Sensitivity in Cancer (GDSC) database for drug sensitivity and gene expression, we identified 8 drugs targeting the apoptosis pathway involving targets of BCL-2, BIRC5, Procaspases, RIPK1, TRAIL, and XIAP." (PMID 31964418, 2020). "Yet, it should be noted that recent work of the Letai group has questioned BDA-366 as an on-target inhibitor of Bcl-2 proteins, indicating that BDA-366 can kill cancer cells independently of Bcl-2." (PMID 32708132, 2020). "By using a network biology-based approach, we were now for the first time able to derive protein activity of BCL-2, BCL-XL, and MCL-1 in a pan-cancer cohort (NCT/DKTK MASTER cohort)." (PMID 33070156, 2020). "Dysregulation of the anti-apoptotic members BCL-2, BCL-xL and MCL-1 have been widely described in carcinogenesis, cancer progression and chemotherapy resistance." (PMID 32131385, 2020). "Numerous studies suggested that abnormal activation of the PI3K/AKT signaling pathway contributed to the upregulation of Bcl-2 expression, which leads to apoptosis-mediated MDR in many cancer therapies." (PMID 32973135, 2020). "As cancer cells display high levels of proapoptotic BH3-only proteins due to oncogenic stress, they are sensitive to Bcl-2-antagonizing therapeutics such as venetoclax." (PMID 32943617, 2020). "However, overexpression of Bcl-2 alone is not significant to cause cancer." (PMID 33551748, 2020). "Since cytokines such as TNF can influence the expression and/or activity of Bcl-2 and caspase 3, circulating chemokine/cytokine-mediated changes in pro-apoptotic and anti-apoptotic proteins in skeletal muscle could have a profound impact on skeletal muscle function in cancer patients." (PMID 31941005, 2020). "The observed cytostatic effects are in agreement with previous studies showing that STAT3 can protect cancer cells from the apoptotic effects of many individual drugs: STAT3 activity controls the expression of pro-survival genes such as MCL1, BCL2 and BCL2L1." (PMID 32231398, 2020). "Bcl-2 is an oncogene that blocks mitochondrial outer membrane permeabilization and inhibits apoptosis, and it is always overexpressed in MDR of cancers." (PMID 32973135, 2020). "The subgroups include proliferation genes (Ki67, STK15; Survivin, CCNB1, MYBL2), invasion genes (MMPP11, CTSL2), HER2 genes (GRB2, HER2), estrogen genes (ER, PGR, BCL2, SCUBE2), and other cancer related genes (GSTM1, CD68, BAG1)." (PMID 33665165, 2020). "Efforts in cancer research have found ABT263 (navitoclax), a potent inhibitor of BCL-2 and BCL-xL anti-apoptotic proteins, can be used to treat lymphomas and other types of cancer." (PMID 32295081, 2020). "Through the microscale thermophoresis (MST) experiment in SW1990 cancer cells, the Kd value of BH3 peptide bound to Bcl-2 was lower than that of luteolin bound to Bcl-2." (PMID 33379233, 2020).
cancer (continued). "This indicated that the anti-cancer effect of CKD-581 would be dependent on other BCL-2 family proteins, such as BCL-2 and BCL-XL, in SU-DHL-4 cells." (PMID 32575557, 2020). "B-cell CLL/lymphoma 2 (BCL-2)-like 11 (BIM), a pro-apoptotic member of the BCL-2 family, is required for TKIs to induce apoptosis in kinase-driven cancers." (PMID 32900991, 2020). "Further, the effects of mono-selective BCL2 inhibitors such as ABT-199 (also known as Venetoclax) and S55746 (also called BCL201 or Servier-1) were also reported in cancer research." (PMID 33126914, 2020). "Suppression of the anti-apoptotic proteins MCL1, BCL2, and BCL2L1 by BH3 mimetics has been well-known to induce the BAX/BAK-modulated mitochondrial death pathway of pro-apoptotic proteins in cancer cells." (PMID 32486166, 2020). "For instance, siRNAs can down-regulate expression of Bcl-2,STAT3, and elF5A2 to interfere with cancer cell proliferation." (PMID 33095554, 2020). "Among them, genes such as BCL2, CSNK2A1, EGFR, PDGFRA, VEGFA, etc., which have been proved to be targets of anti-cancer drugs, were proposed to provide general administrations for pan-cancers." (PMID 32523951, 2020). "Previous studies have shown that in cancer progression, LRPPRC interacts with Beclin 1 and Bcl-2 and forms a ternary complex to maintain Bcl-2 stability, resulting in the maintenance of mitochondrial homeostasis and mitochondrial function." (PMID 32898195, 2020). "The phenotypes of cancer cells are CD20+, CD79a+, bcl2+, CD10–, bcl 6+/–, FOX-P1, and MUM-1/IRF-4 positive." (PMID 32528871, 2020). "Many anti-apoptotic proteins in the intrinsic apoptosis pathway, such as Bcl-2, B cell lymphoma-extra large (Bcl-xL), Mcl-1, and some IAP proteins, are overexpressed in human cancers." (PMID 33172112, 2020). "In the wake of inhibitors targeting BCL-2 and BCL-XL, MCL-1 is emerging as an increasingly promising target given its role in malignant cell survival and resistance to various anti-cancer therapies." (PMID 32335811, 2020). "A series of high-affinity, small-molecule Bcl-2 inhibitors have been developed, and the BH3-mimetic compound and Bcl-2-specific inhibitor Venetoclax (ABT-199) has been approved by the Food and Drug Administration for cancer treatment." (PMID 32587235, 2020). "AT101 induces a high level of NOXA protein in carcinoma cell lines and sensitizes them to BCL-XL and/or BCL2 inhibitors in a NOXA-dependent manner." (PMID 32824203, 2020). "For example, to avoid PARPi relapse and the emergence of chemoresistant cancer cells, we propose the removal of PARPi-induced senescent cells using senolytic drugs like ABT-263 (Navitoclax), an inhibitor of Bcl2 and Bcl-XL18,20,21." (PMID 31186408, 2019). "When combined with a pro-apoptotic agent/B Cell Lymphoma 2 (BCL2) inhibitor, the effectiveness of the combination regimen was super-additive compared to either treatment alone and was selective for MSL cancers." (PMID 31448050, 2019). "Bcl‐2, Bcl‐XL, survivin, and XIAP have been involved in the resistance of cancer cells to chemotherapy." (PMID 31361391, 2019). "Some evidence suggests that LKB1 loss is involved in the upregulation of antiapoptotic proteins of the B-cell lymphoma 2 (BCL-2) family, implying mitochondrial priming in LKB1-defective cancer." (PMID 31781355, 2019). "We also found significant positive correlations between cancer‐related cytokine TNF‐α and (a) bcl‐2 (r > 0.1, P < 0.0001); (b) ΔNp63, c‐REL (r > 0.97, P < 0.0003); (c) WNT5A (r > 0.88, P < 0.01)." (PMID 31173474, 2019). "The target genes of miR-184a identified in cancer are USP4, ROCK1, ERBB3, BCL-2, WNT10B, and CDC25B." (PMID 31052530, 2019).
cancer (continued). "The first, highly selective BCL2 inhibitor venetoclax (ABT-199) binds specifically to BCL2 and displaces BH3 domain-only proteins to trigger BAX/BAK-mediated mitochondria-induced apoptosis of cancer, including AML cells." (PMID 30647404, 2019). "Other target genes in our study including ADCY1, BCL2, BDKRB2, CALM1, and CCND1 have been proved to play important roles in multiple pathways of cancer progression." (PMID 31775867, 2019). "BCL-2 functions by inhibiting the pro-apoptotic proteins (e.g., BAD and BAX) in inducing cell death, thus, prolonging the survival of the cancer cells." (PMID 31064156, 2019). "Myc is an oncogene that is often dysregulated in many cancers, and depletion of c-Myc impairs autophagy flux, thereby reducing phosphorylation of JNK and Bcl2." (PMID 31685029, 2019). "SMIs against BCL-2, IDHs, BRAF, PI3 kinase, mTOR, PARP, and CDKs have become the mainstay in the treatment of a variety of cancer types." (PMID 31807308, 2019). "The applicability of the ABv+anti-PD-1 combination for treating other cancer types with high MYC and BCL-2/BCL-XL status is currently being investigated in preclinical models." (PMID 30728358, 2019). "While LMTK2-dependent regulation of BIM was more evident in non-cancer cell lines, other members of the BCL2 family, such as BCL2 and BCL-xL, were regulated by LMTK2 mainly in fully transformed cancer cells." (PMID 30761001, 2019). "Previous studies showed that the expression level of Pnn is associated with ERK signaling-mediated stress response to glucose deprivation in cancer cells; and activation of ERK signaling mediates Bcl-2 upregulation in various cell types." (PMID 31167655, 2019). "Astaxanthin and curcumin downregulated Bcl-2, Bcl-xL and IAP, upregulated Bax, and induced the mPTP opening and apoptosis in cancer cells." (PMID 31108962, 2019). "It is known that bcl-2, cIAP-2, livin, survivin and XIAP are the anti-apoptotic markers that prevent cancer cells undergoing apoptosis." (PMID 31521140, 2019). "EYA2 promotes cell proliferation and invasion as well as cancer progression by regulating docetaxel sensitivity and mitochondrial membrane potential, possibly via the AKT/Bcl-2 axis." (PMID 31317026, 2019). "Compound 1d remarkably reduced the expression of BCL-2 in SNB-19, A549 and MDA-MB231 cancer lines, but there was a slight increase in Caco-2 cell line." (PMID 31801304, 2019). "Such an inverse correlation between levels of BCL2 and BCL-XL has been observed in a number of cancers." (PMID 31068951, 2019). "This combination strategy may offer effective repression of most of the cancer-relevant antiapoptotic BCL2 family members, thus broadening the impact of both compounds to a variety of indications and overcome the resistance to the current BCL2/BCLxL-targeting agents." (PMID 30635584, 2019). "For example, the combination of the BCL-2 inhibitor and MCL1 inhibitor was synergistic when cancer cells were either dependent on MCL1, or the BCL-2 family contributed to the emerging resistance." (PMID 31370269, 2019). "The simulation showed that cytosolic Bcl-2, XIAP, caspase 3 and other protein expression regulated when a cancer cell would become sensitized to TRAIL via Yoda1 and the degree of sensitization." (PMID 31685811, 2019).
cancer (continued). "Further, using BH3 peptides with specificity for individual anti-apoptotic proteins, such as BCL-2, BCL-xL or MCL-1, the dependency of different cancers types on these various pro-apoptotic proteins can be determined." (PMID 31717784, 2019). "Overexpression of BCL2A1 in cell lines has been found to promote resistance to different cancer drugs including the BH3 mimetic ABT-737, a specific inhibitor targeting Bcl-2, Bcl-xL, and Bcl-w." (PMID 31825969, 2019). "Honokiol from magnolia is another example of a drug able to induce death of a variety of cancer cells by triggering PTP opening and to overcome BCL-2 and BCL-XL-mediated apoptotic resistance." (PMID 31159324, 2019). "We show that in HCT116 cancer cells, mitochondrial amplification is required for TRAIL-induced cell death since stable overexpression of BCL-2 reduced TRAIL-induced cell death." (PMID 31248045, 2019). "miR-205 actively targets the 3'UTR of some key genes such as AR, BCL2, ERBB3, PTEN, and VEGF-A that play important roles in cancer cell invasion and metastasis." (PMID 31756185, 2019). "Because BCL-2 and BCL-xL inhibitors fail to target MCL-1, MCL-1 expression is an obvious potential mechanism by which cancer cells resist treatment with ABT-263, and this mechanism has been demonstrated in some cancer models." (PMID 30728900, 2019). "H-scores of p68 and RelA followed similar trends with H-scores of Bcl-2, Bcl-xL, Survivin and XIAP in both normal and carcinoma samples." (PMID 31351496, 2019). "In solid tumors, however, cancers appear more dependent on fellow anti-apoptotic protein BCL-xL, and to a lesser degree MCL-1, than BCL-2." (PMID 30234143, 2018). "Aberrant increases in the level of anti-apoptotic Bcl-2 proteins such as BCL-2, MCL-1 or BCL-XL prevents apoptosis, this both promotes cancer and allows resistance to cancer therapy-induced cell killing." (PMID 29339815, 2018). "In different cancer models, HMGA2 act as an apoptosis inhibitor inducing BCL2 expression and exerting an opposite effect on the Caspase activity." (PMID 29487711, 2018). "miR-15a inhibits several important genes (BCL2, BMI1, YAP1 and DCLK1), decreasing cancer progression and resistance." (PMID 29416778, 2018). "A peptide tool, called Bcl-2/IP3 receptor disruptor-2 (BIRD-2), was developed to disrupt Bcl-2/IP3R complexes, triggering pro-apoptotic Ca2+ signals and killing Bcl-2-dependent cancer cells." (PMID 30416758, 2018). "Effect of satureja khuzestanica extract (SKE) on expression of molecular markers of apoptosis (Bax, Bcl-2, and caspase 3) in MCF-7 cancer cells." (PMID 29755565, 2018). "MC2884 results in down-regulation of anti-apoptotic drivers such as BCL2 and BCLX(L), mitochondrial modulation and in activation of related death pathways that kill cancer cells in a selective manner." (PMID 29876013, 2018). "MiR-34a exerts its regulative role for cell cycle, differentiation, apoptosis, cancer cell progression and metastasis by targeting genes such as SIRT1, Bcl-2 and HMGI-C." (PMID 29854296, 2018). "Of the BAX/BAK-like BCL-2 protein subfamily, the role of BOK is just recently being explored in the context of human cancers." (PMID 29374142, 2018). "NuBCP-9 treatment exposed the Bcl-2 BH3 domain and induced apoptosis preferentially in paclitaxel resistant H460 cancer cells." (PMID 29899843, 2018).
cancer (continued). "Protective role of myricetin against cancer was demonstrated in HCT-15 cells by DNA condensation, suppression in Bcl-xL and Bcl-2 expression, and increase in the release of mitochondrial AIF." (PMID 30597838, 2018). "Lc3b mRNA (p < 0.05) was increased by cancer whereas the protein content of LC3I, p-ULK1Ser757 as well as total ULK1 and Bcl-2 and p62 mRNA were unaltered." (PMID 30713500, 2018). "The promoters of both Bcl-2 and Bcl-xL contain STAT3 binding sites and can be upregulated by STAT3 in cancer cells." (PMID 30618745, 2018). "The estimated IC50 was 4.6 nM, lower than in the MYC/BCL2 DHL cell lines tested in this study (Su-DHL-10, 8.5 nM; Nu-DHL-1, >10.0 nM) and than in a panel of various cancer cell lines reported previously (11–37 nM)." (PMID 30323893, 2018). "In this section, we will review the miRNA-mediated post-transcriptional control of BCL2, MCL1, BCLxL, BCLW, and BFL1, and their identified roles in cancer biology and anti-cancer drug response." (PMID 29361709, 2018). "Although ABT199 is often considered to be effective only in BCL2 dependent cancers, our study indicates that it can also be used to increase cisplatin effectiveness in TNBC cells that express both BCL(X)L and BCL2, albeit at higher concentration than WEHI-539." (PMID 29352235, 2018). "Altogether, these data demonstrate that S55746 kills cancer cells through on-target activity, meaning activation of a BAX/BAK-dependent mitochondrial apoptotic pathway by direct inhibition of the BCL-2 pro-survival protein." (PMID 29732004, 2018). "Using this approach, we mapped cellular dependencies and co-dependencies on BCL-2, BCL-XL, and MCL-1 across a large number of primary and established cancer cell lines representing 10 distinct cancer types." (PMID 30158527, 2018). "Impact of hybrids 4m and 7b on the expression levels of Bcl-2 and Bax and on the active caspase-3 level in MDA-MB-231 cancer cells treated with each hybrid at its IC50 concentration." (PMID 29895744, 2018). "Effect of compounds 6a and 6e on the active caspases-3 level, and the expression levels of Bcl-2 and Bax in MDA-MB-231 cancer cells treated with each compound at its IC50 concentration." (PMID 29281924, 2018). "Remarkably, co-administration of the Bcl-2 inhibitor GDC-0199 (25 mg/kg, daily, i.p., for 21 days) strikingly potentiated the anti-cancer activity by ABC294640, leading to profound inhibition of C33A tumors." (PMID 29416779, 2018). "Correspondingly, HeLa cells were treated with FSK and probed for its effect on potent established cancer markers like PP2B, IL-6, NOS2, Caspase3, Bcl2, and Bax." (PMID 30558287, 2018). "In fact, these are involved in the induction of the expression of the anti-apoptotic protein Bcl-2, the inactivation of the pro-apoptotic p38/MAPK signaling, and the inhibition of the caspase-3-dependent pro-apoptotic pathway in E2-sensitive cancer cells." (PMID 30189583, 2018). "Disarib showed selective cytotoxicity in BCL2 high cancer cell lines, and CLL patient primary cells, over BCL2 low cells." (PMID 29460395, 2018). "The downregulated genes were associated with cell cycle, TGF-β signaling, FoxO signaling, HIF-1 signaling, and cancer (CDKN1B, FLT3, PDK1, FOXO1, BCL2, ERG), suggesting potential positive regulation of these pathways by SHARP1 to maintain MLL-AF6 AML activity." (PMID 29692408, 2018). "Effect of compound 6n on the active caspases-3, -8 and -9 levels, and the expression levels of Bcl-2, Bax and cytochrome C, respectively, in MCF-7 cancer cells treated with the compound at its IC50 concentration." (PMID 29560733, 2018).